BCL11A (BCL11 transcription factor A)
Diseases named in the same sentence as BCL11A in open-access papers (continued):
Sharing a sentence is not in itself a finding about the gene and the disease.
breast cancer (continued). "The requirement of Bcl11a in the established mouse mammary tumours is consistent with the decreased tumourigensis of BCL11A knockdown breast cancer cells and underscores its candidature for therapeutic development." (PMID 25574598, 2015). "Only when mammary tumours were detected and measured, the mice were then injected with tamoxifen to induce Bcl11a deletion." (PMID 25574598, 2015). "Here, we report that the transcription factor BCL11A is overexpressed in TNBC including basal-like breast cancer (BLBC) and that its genomic locus is amplified in up to 38% of BLBC tumours." (PMID 25574598, 2015). "Analysis of BCL11A expression in a panel of breast cancer cell lines revealed that BCL11A is highly expressed in TNBC lines but is undetectable in any of the luminal cell lines tested." (PMID 25574598, 2015). "Expression was also detected in RNA isolated from Brca1-/- mouse mammary tumors: Bcl11a was detected in seven of eight tumors, and Sox11 was detected in two of eight tumors." (PMID 23506684, 2013). "Moreover, breast cancer tissues exhibited higher BCL11A mRNA and lower uc.57 mRNA levels compared to precancerous breast cells." (PMID 40689201, 2025). "Finally, we validated that RAD9A, HSPA1B, GATA2, IGF2R, CD200, ERCC8, and BCL11A genes are consistently dysregulated in the doxorubicin-induced human-induced pluripotent stem cell-derived cardiomyocytes (hiPSC-CMs) derived from breast cancer patients." (PMID 37684436, 2023). "Moreover, RBBP4/7 can bind to BCL11A, a key protein that plays a tumorigenic role in triple-negative breast cancer and breast cancer stem cells, and recruit NuRD, PRC2 and SIN3A to initiate transcriptional repression." (PMID 38028543, 2023). "Studies found that BCL11A could participate in epithelial-mesenchymal transition and promote breast cancer metastasis by the Wnt/β-catenin signaling pathway." (PMID 35909289, 2022). "It has been shown in breast cancer cells that BCL11A positively regulates MDM2 expression." (PMID 32266150, 2020). "BCL11A expression was higher in breast cancer tissues than in precancerous tissues." (PMID 29179465, 2017). "BCL11A was overexpressed in breast cancer tissues than in precancerous tissues." (PMID 29179465, 2017). "Therefore, uc.57 and BCL11A are potential therapeutic biomarkers in TAM-resistant breast cancer patients." (PMID 29179465, 2017). "Moreover, levels of uc.57 mRNA were lower and BCL11A mRNA were higher in breast cancer tissues than in precancerous breast tissues." (PMID 29179465, 2017). "BCL11A has a critical role in breast cancer stem and progenitor cells." (PMID 29179465, 2017). "We have demonstrated here that the transcription regulator BCL11A is a novel breast cancer gene." (PMID 25574598, 2015). "Four transcription factors (Bcl11a, Grhl3, Prox1, Sox11) activated in Brca1-/- mouse tumors and basal-like human breast cancers across multiple datasets were chosen for validation studies, and all were confirmed to be embryonic-enriched and highly expressed by some tumors." (PMID 23506684, 2013). "However, BCL11A is a zinc-finger protein, and other members of this class have been shown to regulate estrogen receptor expression in breast cancer cells." (PMID 24312637, 2013). "BCL11A levels were consistently higher in basal-like breast cancers compared with other subtypes." (PMID 23506684, 2013). "Inhibition of RBBP4-BCL11A complex formation by BCL11A peptide inhibitor may decrease aldehyde dehydrogenase-positive breast cancer stem cells; hence, targeting interactions between RBBP4 and oncogenic transcription factors may provide opportunities for intervention." (PMID 41278204, 2025). "BCL11A, MLLT3, ZNF521, PHC1, and PCGF3 also showed subtype-specific dysregulation in breast cancers; BCL11A, ZNF521, and PHC1 were specifically downregulated in luminal subtype cancers relative to their matched normal tissue." (PMID 39545637, 2024).
breast cancer (continued). "We detected 465 DTU genes (FDR < 0.01), including 46 cancer-related genes and 10 genes specifically related to breast cancer, including ESR1 and BCL11A." (PMID 34811492, 2021). "From ~2,000 breast cancer cases in METABRIC5, CN gains at the BCL11A genomic locus were identified in 62 patients, which also correlates with high BCL11A expression." (PMID 25574598, 2015). "Although Bcl11a is important for DMBA-induced mammary tumour formation, it is more clinically relevant if it has functions in mammary tumour progression and maintenance." (PMID 25574598, 2015). "Both BCL11A and SOX11 belong to the top 20 transcriptional regulators that correlate with the core ES signature found activated in aggressive breast cancers." (PMID 23506684, 2013). "Based on this, the human TNBC cell line MDA-MB-231 was chosen due to strong expression of BCL11A and CHD8, and the luminal breast cancer cell line MCF-7 was selected as a control due to expression of CHD8 but no BCL11A expression." (PMID 40328966, 2025). "None of the other de novo SNVs (i.e., BCL11A, BCOR, and COL1A1) was recurrent in more than one sample nor has been linked to treatment failure in breast cancer, leaving the evolution of resistance unexplained in 12 of 13 replicates." (PMID 38527495, 2024). "Moreover, they showed that low expressions of BCL11A and HDAC1/2 are correlated with better prognosis of breast cancer patient, which supports the clinical benefits of IO relationship normalization." (PMID 37269056, 2023). "In conclusion, through cancer genomics, in vitro assays, experimental xenograft models and mouse genetics, we have demonstrated in this study that BCL11A is a new breast cancer gene and a critical regulator in normal mammary epithelial development." (PMID 25574598, 2015). "Finally, we validated the expression level of immune-related genes in breast cancer patients-derived cardiomyocytes with doxorubicin-induced cardiotoxicity and found that the level of RAD9A, HSPA1B, GATA2, IGF2R, CD200, ERCC8, and BCL11A genes are consistently dysregulated." (PMID 37684436, 2023). "To further explore the expression of CHD8 in TNBC we analysed PDX samples which identified that, at the protein level, BCL11A and CHD8 are specifically upregulated in TNBC PDXs but not in Luminal breast cancer PDXs." (PMID 40328966, 2025).
lymphoma (21 papers, 2006 to 2025). A malignant (clonal) proliferation of B- lymphocytes or T- lymphocytes which involves the lymph nodes, bone marrow and/or extranodal sites. "BCL11A is required for the function of several cell types, and ablation of BCL11A function can cause undesirable downstream effects, such as leukemia and lymphoma; therefore, targeting BCL11A should be restricted to the erythroid lineage." (PMID 30603654, 2019). "Aberrant activation of the proto-oncogene B-cell lymphoma/leukemia 11A (BCL11A) has been implicated in the pathogenesis of leukemia and lymphoma." (PMID 23758992, 2013). "BCL11A, the B-cell associated transcription factor leukaemia 11A gene encoding a zinc-finger protein, acts as a transcriptional repressor critical to lymphoma malignancy." (PMID 21081927, 2011). "At the same time, different subtypes of BCL11A may be associated with different types of lymphomas, but there have been few studies to date." (PMID 39857257, 2025). "Although BCL11A is an essential regulator of normal lymphocyte development in mouse embryos and its expression is elevated in some lymphoma patients, the mechanism underlying this is unknown." (PMID 25978455, 2015). "Bcl11A is a zinc-finger transcription factor, which is an essential regulator of lymphopoiesis in mice, and its elevated expression has been associated with some lymphoma patients in humans." (PMID 22348085, 2012). "High expression of BCL11A was also demonstrated in cancer cells, such as lymphomas, B-cell leukemias, prostate cancer, and colorectal cancer." (PMID 37185699, 2023). "These include the lymphoma related BCL11A gene, the IKZF2 gene involved in lymphocyte development or the transcription initiator GTF2H1." (PMID 36961799, 2023). "For example, Bcl6 and Bcl11a, which are marker genes for lymphoma, showed higher gene expression levels in ES cells, even though located in B compartment in ES cells." (PMID 30894186, 2019). "For instance, B-cell eCGIs are enriched for regions binding key TFs involved in B-lymphopoiesis and lymphoma pathogenesis (such as BCL11A, EBF1, IKZF1 and SPI1), whereas ESC-specific eCGIs are enriched for binding of NANOG, a key TF regulating pluripotency." (PMID 26512062, 2016). "Understandably, we also observed the B-cell lymphoma protein (BCL6 and its paralog coding gene BCL6B) and other leukemia-related disease genes involved in lymphoma pathogenes, such as BCL11A." (PMID 25649207, 2014). "To select a suitable cell line model, we assessed a number of leukaemia and lymphoma cell lines for expression of BCL11A-XL protein." (PMID 23975195, 2013). "Previous studies have documented elevated RNA levels of BCL11A in GC-derived lymphomas such as B-CLL, FL, and Burkitt's lymphoma." (PMID 16704730, 2006). "Fusion or gain of REL, a member of the NF-κB pathway, and BCL11A was reported to be enriched in transformed lymphoma, and this may be a genomic marker for disease progression to clinically more aggressive forms." (PMID 27835906, 2016). "Furthermore, knockdown of BCL11A leads to increased rates of apoptosis in lymphoma cell lines." (PMID 25517766, 2014). "In particular, recurrent gain/amplificationof the 2p15-p16.1 locus, where REL, BCL11A, PAPOLG,PUS10, and USP34 genes reside, is a common observationin different lymphoma types including classical Hodgkinlymphoma and transformedfollicular lymphoma." (PMID 31410080, 2019). "FISH analyses using BAC clones covering lymphoma breakpoints (BCL2, BCL6, BCL11A, CCND1, CCND3, IG-H/K/L, JAK2, LMO2, MYC, PAX5, REL) all tested normal, excluding rearrangements at these loci." (PMID 26599546, 2015). "Consistent with previous studies on lymphomas, we identified REL and BCL11A located at 2p16.1, and BCL2 at 18q21.3 being among the genes, whose expression was linked with copy number gains." (PMID 24625556, 2014). "We performed a survival analysis and found that high BCL11A expression correlated with better survival and DFS, results similar to previous data on lymphoma." (PMID 23758992, 2013).
lymphoma (continued). "Conversely, post-GC lymphomas, regardless of the cytogenetic status of 2p16.1, express significantly lower RNA levels of BCL11A isoforms (unpublished observations)." (PMID 16704730, 2006).
triple-negative breast carcinoma (19 papers, 2015 to 2026). An invasive breast carcinoma which is negative for expression of estrogen receptor (ER), progesterone receptor (PR), and human epidermal growth factor receptor 2 (HER2). "In this study we describe our approach for the identification of triple negative breast cancer (TNBC)-specific protein–protein interactions focusing on the oncogene BCL11A." (PMID 40328966, 2025). "While ANP32E, AURKB and BCL11A induce tumor progression in triple-negative breast cancer cells, downregulation of CDK2-AP1 enhances tumor growth through cell cycle regulation." (PMID 37007972, 2023). "The overexpression of BCL11A at the mRNA and protein levels was also demonstrated in B-cell lymphoma, B-cell chronic lymphocytic leukemia and triple-negative breast cancer." (PMID 37372998, 2023). "Mir-574-5p targets Bcl11a and Sox2 to attenuate proliferation in triple-negative breast cancer cells and governs cell proliferation through the Wnt/β-catenin pathway in PTC-1 cells." (PMID 36207684, 2022). "Recent studies uncovered that BCL11A was a critical oncogene in many other cancers like triple-negative breast cancer, lung squamous carcinoma, colorectal cancer, and laryngeal squamous cell carcinoma." (PMID 34938655, 2021). "BCL11A is over-expressed and its genomic locus frequently amplified in triple-negative breast cancer gene, suggesting a tumorigenic role in these tumors." (PMID 32850701, 2020). "As reported, circEPSTI1 promotes triple-negative breast cancer cell proliferation and apoptosis through sponging miR-4753 and miR-6809 to regulate the BCL11A level." (PMID 30956729, 2019). "Through binding to microRNA-4753 and microRNA-6809, circEPSTI1 upregulates expression of B cell CLL/lymphoma 11A (BCL11A), promotes the proliferation of triple-negative breast cancer cells, and inhibits their apoptosis." (PMID 30619334, 2018). "Recently, it was reported that BCL11A is a novel triple-negative breast carcinoma oncogene, which was expressed in 66.7 % (16/24) of triple-negative breast carcinomas." (PMID 27113214, 2016). "This locus contains the transcription factor BCL11A, a known oncogene in triple-negative breast cancer and B-cell lymphoma, that has been described as integral to the pathology of lung squamous carcinoma through its interaction with SOX2 to control the expression of epigenetic regulators." (PMID 37871126, 2023). "In triple-negative breast cancer, circGFRA1 acts as miR-34a ceRNA to regulate GFRA1 expression, while circEPSTI1 promotes triple-negative breast cancer cell proliferation through a novel pathway by sponging miR-4753 and miR-6809 and upregulating the oncogene BCL11A." (PMID 30626395, 2019). "This was consistent with a previous report that BCL11A promoted triple-negative breast cancer." (PMID 29179465, 2017). "Additionally, BCL11A has also been shown to be related to triple-negative breast cancer." (PMID 41363728, 2026). "This study uses multi-omics and biophysical analyses to identify chromatin remodeler CHD8 as a triple negative breast cancer (TNBC)-specific, targetable interaction partner of oncogene BCL11A." (PMID 40328966, 2025).
B-cell lymphoma (17 papers, 2010 to 2025). "BCL11A is a developmental regulator expressed in haematopoietic and neural tissues whose overexpression is associated with acute leukaemia and B-cell lymphoma." (PMID 23975195, 2013). "CRISPR: clustered regularly interspaced short palindromic repeats; TTR: transthyretin; BCL11A: B-cell lymphoma/leukemia." (PMID 41211267, 2025). "This therapy, developed by Vertex Pharmaceuticals and CRISPR Therapeutics, uses CRISPR to edit the patient's hematopoietic stem cells, enabling them to produce fetal hemoglobin by altering the B-cell lymphoma/leukemia (BCL11A) gene." (PMID 41211267, 2025). "BCL11A is oncogenic and aberrantly expressed in several hematopoietic malignancies, including leukemia, B-cell non-Hodgkin lymphoma (B-NHL), and Hodgkin’s disease (HD)." (PMID 32625084, 2020). "Several reports have shown that BCL11A is oncogenic in B‐cell lymphoma, B‐cell chronic lymphoblastic leukemia, and several solid tumors." (PMID 32625084, 2020). "Knock-down of BCL11A led to apoptosisof a B-cell lymphoma cell line in the presence of achemotherapeutic agent." (PMID 31410080, 2019). "It is noteworthy that knockdown of BCL11A mRNA by small interfering RNA combined with vincristine can decrease cell proliferation and increase cell apoptosis in B-cell lymphoma." (PMID 31654056, 2019). "Western blots indicated that BCL11A-XL is robustly expressed in the B-cell lymphoma DOHH2 cells and U937 myeloid leukaemia cells, whereas expression levels are very low in the erythroleukaemia cell line K562 and the promyelocytic leukaemia HL60 cell line." (PMID 23975195, 2013). "BCL11A acts as a proto-oncogene for B-cell lymphoma, as a recessive oncogene for T-cell lymphoma, and is apparently required for the expression of some globin genes." (PMID 20433734, 2010). "In addition, the results of the study suggested the participation of BCL11A in the development of various types of cancer, such as lung cancer, B-cell lymphomas and leukemias, and prostate and colorectal cancer." (PMID 37185699, 2023). "Furthermore, we summarize publications analyzing c-Rel expression and protein localization in these human B cell lymphomas and discuss the co-amplification of BCL11A with REL." (PMID 31277480, 2019). "BCL11A has been shown to be an oncogene in B-cell lymphoma and triple negative breast cancer." (PMID 30127402, 2018). "Interestingly, some of the AID-induced DSBs occur at sites that are known to be translocated or amplified or deleted in human B-cell lymphomas, such as the B-cell lymphoma 11a gene (Bcl11a/Evi9)." (PMID 28867784, 2017). "BCL11A overexpression is primarily found in B cell lymphoma and B cell leukemia." (PMID 24961604, 2014). "Therefore, our study implies that the combination of BCL11A siRNA transfection plus VCR is an efficacious therapeutic approach for treating B cell lymphomas that express BCL11A." (PMID 24961604, 2014). "Our study implies that BCL11A siRNA in combination with VCR may be a useful approach for improving effective treatment for B cell lymphoma." (PMID 24961604, 2014). "BCL11A is known to be involved in both Hodgkins and non-Hodgkins B-cell lymphoma." (PMID 20433734, 2010).
hemoglobinopathies (17 papers, 2010 to 2025). "Here, we have used a general strategy to assess the capability of two erythroid cell–enriched E3 ubiquitin ligases, TRIM10 and TRIM58, to degrade a POI, BCL11A, which is a validated target for reactivation of HbF in hemoglobin disorders." (PMID 39675716, 2024). "During the era of next‐generation sequencing, the bulk of variants and polymorphisms have been identified in the hemoglobinopathy‐relevant genes, especially in modifier genes, such as the KLF1, BCL11A, and HMIP regions." (PMID 31286593, 2019). "On the other, it raises concern with regards to the inactivation of BCL11A as a target for hemoglobinopathies." (PMID 27453576, 2016). "B-cell lymphoma/leukemia 11A (BCL11A) is a crucial transcriptional regulator, widely recognized for its role in controlling fetal hemoglobin and its potential as a gene therapy target for inherited hemoglobinopathies." (PMID 39857257, 2025). "Whilst deficiency in expression of BCL11A, and expression of fetal globin, is therapeutically attractive for treatment of hemoglobinopathies, primitive erythroid cells do not efficiently enucleate in vitro without the support of macrophages." (PMID 27769165, 2016). "Concluding, the assays developed can be successfully applied for accurate, time and cost efficient simultaneous genotyping of SNPs associated with HbF levels in the BCL11A gene and in the HBS1L-MYB intergenic region in HPFH, β-thalassaemia, SCD or other hemoglobinopathy populations." (PMID 24502199, 2014). "In addition, about 15% of the HbF variance was explained by a polymorphism in BCL11A on 2p15, 19% by an intergenic variant in HBS1L-MYB on 6q23, and 10% by Xmn1 in Europeans without hemoglobinopathies." (PMID 20353593, 2010).